TNFAIP3 (TNF alpha induced protein 3)
Diseases named in the same sentence as TNFAIP3 in open-access papers (continued):
Sharing a sentence is not in itself a finding about the gene and the disease.
cancer (51 papers, 2011 to 2026). A tumor composed of atypical neoplastic, often pleomorphic cells that invade other tissues. "Downregulation of TNFAIP3 is associated with distant metastasis and poor prognosis in cancer patients." (PMID 35984577, 2022). "TNFAIP3 is a well-known negative regulator of the NF-κB signaling pathway, and mutations in this gene are usually observed in cancer, including hematological malignancies, which affect the clinical outcome of patients." (PMID 34526012, 2021). "TNFAIP3, the gene encoding A20, has been documented to be an anti-inflammatory and immune factor and expressed increased abnormally in many types of tumor cells and tissues, which was closely associated with the progression, therapy and prognosis of cancer." (PMID 38750582, 2024). "In addition, somatic deletion and biallelic mutations of TNFAIP3 have been found in B-cell lymphoma, suggesting that A20 plays a role in suppressing cancer." (PMID 34030699, 2021). "Germline loss-of-function variation in TNFAIP3, encoding A20, has been implicated in a wide variety of autoinflammatory and autoimmune conditions, with acquired somatic missense mutations linked to cancer progression." (PMID 33154446, 2020). "However, deletion of PRDM1 and TNFAIP3 on chr6 has been linked to cancer." (PMID 32512761, 2020). "Analysis of TNFAIP3 mRNA expression patterns in 33 cancer types from TCGA revealed significant variation compared to corresponding normal tissues." (PMID 41461391, 2026). "CPTAC proteomic analysis has unveiled significant variations in TNFAIP3 protein expression across multiple cancer types." (PMID 41461391, 2026). "At the transcriptomic level, we found that CCL19 and TRAF3IP3 were protective factors in pan‐cancer, whereas IL11, PTGES, and TNFAIP3 were risk factors." (PMID 40714831, 2025). "Our results reveal hybrid cell upregulation of immune molecules, including CD74, B2M and TNFAIP3, which are known to contribute to cancer cell immune evasion." (PMID 38106024, 2023). "Among them, seven genes (FHL1, SELL, VIM, IGFBP7, TNFAIP3, LCP2, and SLC7AB) were associated with the cancer-immunity cycle." (PMID 35565437, 2022). "Knockout of TNFAIP3 attenuates the ability of proliferation, invasion and migration of cancer cells in vitro." (PMID 35984577, 2022). "In Pt2, one integration located between two cancer-related genes, TNFAIP3 and PERP, yielded increased expression of both genes with statistical significance; however, this integration was due to LASN, indicating integration only in peripheral T cells." (PMID 34786435, 2021). "TNFAIP3 is a well-known natural NF-κB inhibitor, having the potential to treat NF-κB-overactivated diseases such as inflammation and cancers." (PMID 30973327, 2019). "A total of 5 genes were annotated for both cancer and inflammation: Fcgr2b, Egfr, Tnfaip3, Fas and Myd88." (PMID 27566565, 2016). "For another example, the average expression level of TNFAIP3 was ranked at the top 7.4% and 3.2% of all the measured genes in the cancer and normal samples, respectively." (PMID 27796338, 2016). "The observed TNFAIP3 suppression in advanced BRCA likely reflects its dual role in cancer biology." (PMID 41461391, 2026). "TNFAIP3, a key player in the human immune system, exhibits a dual role in cancer biology." (PMID 39724264, 2025). "Therefore, modulating TNFAIP3 expression levels presents a promising approach for the therapy of diverse cancers." (PMID 39724264, 2025). "On the contrary, high expression of OTUD4, OTUD5, and TNFAIP3 could enhance the sensitivity of cancer cells to radiotherapy." (PMID 40469292, 2025). "Our results revealed that the expression of TNFAIP3 was decreased in cancer samples but decreased more under P, indicating that P could reduce inflammation better than S." (PMID 36647133, 2023). "However, some recent studies implied a paradoxical role for TNFAIP3 outside the immune system, suggesting its contributory effects to the proliferation and metastasis of a variety of cancer cells." (PMID 33374641, 2020).
cancer (continued). "Importantly, A20, also known as TNFα-induced protein 3 (TNFAIP3), a key regulator of inflammation and terminator of NF-κB signaling, reduces hepatic inflammation and cancer onset by protecting hepatocytes from TNFα-induced apoptosis under obese conditions." (PMID 30591653, 2018). "The structure of TNFAIP3 could explain its dual role in cancer." (PMID 36056685, 2023). "In most of these cancers, NF-κB is frequently activated by recurrent genetic mutations targeting core components of the B Cell Receptor (BCR) complex, such as CD79A and CD79B, or upstream regulators of the canonical NF-κB pathway, such as MYD88, CARD11, and TNFAIP3/A20." (PMID 36140335, 2022). "Coding sequence (CDS) mutations in TNFAIP3 in TCL patients was explored using exome-sequencing data from 79 patients in our center (Guangdong Provincial People’s Hospital, GDPH) and 544 samples from the Catalogue of Somatic Mutations in Cancer (COSMIC) database." (PMID 34526012, 2021). "In this study, we investigated the TNFAIP3 mutation pattern and its prognostic value for TCL patients from Jinan University (JNU), Guangdong Provincial People’s Hospital (GDPH), Catalogue of Somatic Mutations in Cancer (COSMIC), and Gene Expression Omnibus (GEO) datasets." (PMID 34526012, 2021). "Amongst the differentially expressed CGC genes, we observed and visualized several oncogenes that have been previously studied for their role in different cancers (e.g., TMSB4X and TNFAIP3)." (PMID 37355674, 2023). "A20/TNFAIP3 is significantly upregulated in TNBC, and its expression level is highly correlated with low/poor survival of metastasis-free patients, promoting cancer metastasis via multi-monoubiquitylation, which activates the functions of Snail." (PMID 38201582, 2023). "In Pt2, five integrations with total frequencies of more than 1% were observed near or in cancer-related genes (DPP4, TNFAIP3/PERP, MLLT10, EPS8, and SPINT1)." (PMID 34786435, 2021). "SPARC, RECK, TNFAIP3 and CXCL14 were down-regulated (p < 0.05) in BCBM as compared to primary BC samples irrespectively of the cancer subtype, while for CADM1, this correlation was found in HR positive and TNBC samples." (PMID 24833255, 2014). "Notably, D_FB1 displays elevated levels of other cancer‐ and inflammation‐related genes—such as DNAJB1, ZFP36, JUND, TNFAIP3 and IL6—further underscoring a microenvironment characterised by heightened cellular stress and chronic inflammation." (PMID 41055332, 2026). "TNFAIP3, a key regulator of TNF‐α signaling, plays a dual role in cancer biology, but its precise function in BRCA pathogenesis and immune modulation remains unclear." (PMID 41461391, 2026). "Further, we found six genes—FOXL2, TNFAIP3, CHD1L, HRAS, KIT, CTCF—that occurred in 12 cases that are not on the top 20 list of any of the four common cancers used for comparison." (PMID 32570879, 2020). "TNF-alpha-induced protein 3 (A20), inhibitor of apoptosis (IAP), and cellular FLICE-inhibitory protein (cFLIP) are target genes for the NF-κB cascade rather than the cellular immune system and hence promote cancer cell apoptosis." (PMID 39351437, 2024).
infection (48 papers, 2015 to 2026). The state of being infected such as from the introduction of a foreign agent such as serum, vaccine, antigenic substance or organism. "However, an enhanced upregulation of 9 genes, all involved in the NF-kB pathway (CCL2/MCP1, CCL20, CCL4, CXCL2/MIP2α, IL1A, NFKBIA, PTX3, TNFA, TNFAIP3), was observed after infection with D26 variants, in comparison to the WT." (PMID 33399033, 2021). "Several SNPs were associated with susceptibility to infection and septic shock, one in the univariate analysis (rs6853 at MyD88 gene) and seven with the multivariate model (rs610604, rs6922466, rs7753394, and rs583522 at TNFAIP3 gene; rs6579837, rs73272842, rs3792783 at TNIP1 gene)." (PMID 30813592, 2019). "The genes specifically downregulated over the course of infection by Fasciola miRNAs included Nod1, E2f1, Tnfaip3 and Cdk6 at 6 hrs, and Jam3, Vegfa, Nod1, Uvrag and Nlrc3 at 18 hrs." (PMID 39344634, 2024). "Among them, the differential protein SAA3 and the differential ubiquitinated protein TNFAIP3 not only act as biomarkers of infection and inflammation but are major determinants of inflammatory status and disease progression in many cases." (PMID 37643174, 2023). "Especially, TNFAIP3 belong to tumor necrosis factor were influenced during FAdV-4 infection process and play vital roles in the inflammatory response." (PMID 35774982, 2022). "We also identified an increase in the expression levels of transcripts related to silencing the NF-κB pathway, such as TNFAIP3 (A20) 24 h after infection (1.91)." (PMID 35746747, 2022). "Treatment of infected cells with BI-605906 limited both TNF and TNFAIP3 transcriptional activation following infection." (PMID 35022513, 2022). "Downregulation of multiple pro-inflammatory genes (CCL5, IL6, IL1B) was accompanied by upregulation of anti-inflammatory TNFAIP3 at 48 h post-infection." (PMID 34759825, 2021). "Overexpression of CXCL2, TNFAIP3, ATF3, and CXCL3 increased VEEV-TC-83 infection, suggesting rate limitation associated with these candidate proviral factors." (PMID 33788849, 2021). "The strong EPs 7630-induced inhibition of pro-inflammatory IL1B induction and upregulation of anti-inflammatory TNFAIP3 late post-infection encouraged us to have a closer look at the cytokine secretion profile of epithelial Calu-3 cells." (PMID 34759825, 2021). "Activated CD8+ T cells exhibited increased expression of activation markers CD69 and TNFAIP3 with both infection and vaccination." (PMID 34935643, 2021). "In the present study, we found that replication of PDCoV simultaneously enhanced the expression of endogenous circTNFAIP3 and the TNFAIP3 protein, showing that PDCoV hijacks the expression of the TNFAIP3 gene during infection." (PMID 34781747, 2021). "Since meningitic E. coli PCN033 induced a significant reduction of miR-19b-3p in hBMECs, we therefore investigated the possible expression change of TNFAIP3 during the infection." (PMID 31783671, 2019). "Reduction of TNFAIP3 protein resulted in a 70% inhibition of the infection rate as assessed by N protein levels." (PMID 28355270, 2017). "In agreement with our transcriptome analysis, we observed significant mRNA increases of pro-inflammatory cytokine genes including TNF, IL-6, and TNFAIP3 starting at 4 h post infection, while increases in IFN pathway genes were only observed at 24 h and only in Calu-3 cells." (PMID 35022513, 2022). "Compared with the mock-infected cells, the endogenous pre-mRNA, circRNA, mRNA, and TNFAIP3 protein were synchronously upregulated in PDCoV-infected cells, and the ratio of mRNA to circTNFAIP3 was dramatically increased during the later stages of infection." (PMID 34781747, 2021). "Interestingly, DVG-mediated upregulation of TNFR2 signaling was controlled by MAVS, as MAVS KO cells showed impaired upregulation of surface TNFR2 expression and blunted expression of the pro-survival genes TRAF1, BIRC3, and TNFAIP3 upon infection with SeV HD." (PMID 28986577, 2017).
infection (continued). "It was proved that TNFAIP3, a key factor in NF-κB pathway, could attenuate NF-κB activation during the infection while nAChR, one of important ACh receptor, could also modulate the inflammatory responses through both NF-κB and JAK/STAT pathway." (PMID 26576764, 2015). "Pathways involved in chemokine receptor signaling were also significantly enriched, highlighting the recruitment of immune cells to the site of infection (NFKBIA, NFKBIB, NFKBIE, NFKBIZ, TNFAIP3, REL, BCL3)." (PMID 40634947, 2025). "RNA-seq showed that the expression of ACOD1 and its downstream genes (HMOX1, TNFAIP3, TAP1, ATF3, and NRF2) was significantly upregulated post infection." (PMID 37256871, 2023). "The result suggested that the infection of LV‐YTHDF2 in T98G and LN229 cells reduced the luciferase activity of TNFAIP3‐WT (with m6A sites), and the infection of LV‐Sh‐YTHDF2 in T98G/TR and LN229/TR cells increased the luciferase activity of TNFAIP3‐WT." (PMID 35582627, 2022). "Infection of dTHP-1 cells with three IAV (H1N1) strains of differential replication efficiency showed the strongest ACOD1 and TNFAIP3 induction by the two strains with the highest and the weakest by the strain with the lowest replication efficiency." (PMID 35025971, 2022). "These signaling pathways showed that, after LPS infection, several DEGs were mainly related to immune function, such as up-regulated expression of CCL5, IL8, NFKBIA, TRAF3, and TNFAIP3, and down-regulated expression of MEF2C, MAP2K6, TLR1, TLR2, and IRF5." (PMID 34067819, 2021). "The level of the epigenetic marker at the position of genes WNT10A, JUNB, FOSL2, TNFAIP3, KLF4 and EDN1 was increased, and decreased at the position of genes MYCN and PCSK9, as was demonstrated by using the in vitro HCV-infection systems." (PMID 31216276, 2019). "As shown, both TNFAIP3-KO cell clones (KO#20 and KO#03) showed significant higher levels of proinflammatory factors like TNF-α, IL-6, IL-1β, and CCL2 in response to the infection, as compared to that of the wild-type cells." (PMID 31783671, 2019). "Correspondingly, the TNFAIP3 mRNA transcription, as well as protein expression level in the brain, were significantly increased upon PCN033 infection, while the miR-19b-3p pretreatment significantly recovered this TNFAIP3 upregulation." (PMID 31783671, 2019). "Therefore, we speculate that TNFAIP3 might participate in inhibiting the NF-κB signaling during the early and late infection stages of an EV-F7 infection, implying that it might also regulate innate immune signaling or be involved in antivirus responses to infection with EV-F7." (PMID 30545363, 2018). "This was supported by the upregulation of the NF-kB inhibitor genes NFKBIA and NFKBIZ, the AP-1 transcription factor complex genes FOS, JUN, FOSB and JUNB as well as other NF-kB target genes such as TNFAIP3, RELB, NR4A2, DUSP1 and CD69 in response to infection." (PMID 37700317, 2023). "Similar to WT STm infection, genes involved in the regulation of immune responses (ATF3, BATF3, ETS2, IRF9, NFκB2, MAFA, TNFAIP3), effector functions, (CCL4, CD200L, CD40, CD72, CD80, IL18) and TLR signaling, (EAF2, TLR15, TRAF3IP2, TOLLIP) were upregulated after ΔprgH STm infection in both models." (PMID 37854334, 2023). "Further supporting this hypothesis, the upregulation of an NF-kB signature, including TNFAIP3, NFKBIA and FOS, was also induced in an epithelial cell line model 8 h after infection with SARS-CoV-2." (PMID 37700317, 2023). "TNFAIP3, PPP1R15A, NFKBIA, and IFIT2 had shown bimodal gene expression in various immune cells from severely infected patients compared to healthy or moderate infection cases." (PMID 33602138, 2021). "Depletion of TNFAIP3, ATF3, TAF7, and TRMT10C mildly to moderately reduced VEEV-TrD infection." (PMID 33788849, 2021).
infection (continued). "We subsequently knocked out TNFAIP3 from hBMECs by applying the CRISPR/Cas9 approach and demonstrated a significant increase of proinflammatory cytokine and chemokines, which is similar to those with miR-19b-3p mimic transfection during the infection." (PMID 31783671, 2019). "Meanwhile, anti-inflammatory factors such as TNFAIP3, NFKBIA, NFKBIZ, SOCS1, SOCS3, and IL-10 were elevated, with the reverse trends for the inflammation-inducing genes PPBP and MARCO at 38 hpi, suggesting that the pro- and anti-inflammatory responses might coexist in PAMs during YC-2020 infection." (PMID 36338035, 2022).
neurodegenerative disease (4 papers, 2014 to 2025). A disorder of the central nervous system characterized by gradual and progressive loss of neural tissue and neurologic function. "These ‘risky’ TNFAIP3 SNPs, akin to those seen in A20 HT mice, may cause low-grade inflammation in the brain, predisposing patients to neuroinflammation and neurodegenerative diseases." (PMID 25026958, 2014). "In summary, our results reveal a new function of TNFAIP3, which may provide a potential and an attractive therapeutic strategy for degenerative diseases." (PMID 33226960, 2020). "Moreover, autophagy triggered by TNFAIP3 can ameliorate the degeneration of inflammatory human NPCs, providing a potential and an attractive therapeutic strategy for degenerative disease." (PMID 33226960, 2020).
renal disorder (4 papers, 2010 to 2025). "In our subjects, preferential association with renal disorder was also observed for TNFAIP3." (PMID 20849588, 2010). "TNIP1 (TNFAIP3-interacting protein 1), exerting similar anti-inflammatory function as TNFAIP3, shows a trend toward upregulation in the glomerular compartment in human kidney diseases." (PMID 40072109, 2025). "To assess the relevance of our cell and mouse model findings in human renal disease, we analyzed the transcriptional levels of TNFAIP3 and selected genes involved in apoptosis and anoikis, NF-κB regulation, and cell attachment within both the glomerular and tubular compartments." (PMID 40072109, 2025). "Finally, we analyzed TNFAIP3 transcription levels alongside genes involved in apoptosis, anoikis, NF-κB regulation, and cell attachment in glomerular and tubular compartments of kidney biopsies of patients with various renal diseases." (PMID 40072109, 2025). "Further, TNFAIP3 is upregulated in the glomeruli of SLE and RPGN patients, while we did not observe expression dysregulation in glomeruli in other kidney diseases." (PMID 40072109, 2025).
bacterial infection (3 papers, 2019 to 2022). "In the present study, TNFAIP3 was found to be upregulated after Y. ruckeri infection, demonstrating that this gene was involved in immune response of rainbow trout during bacterial infection." (PMID 33882827, 2021). "Despite these findings, the CNS-related TNFAIP3 functionalities in the perspective of bacterial infections have rarely been acknowledged in the past." (PMID 31783671, 2019).
hematological malignancies (3 papers, 2011 to 2021). "Worth mentioning, TNFAIP3 is targeted by promoter methylation in various hematological malignancies." (PMID 31120955, 2019). "In our previous study, mutations in the non-coding sequence (non-CDS) region of TNFAIP3 were also found in T-cell hematological malignancies." (PMID 34526012, 2021).
intestinal disease (3 papers, 2011 to 2025). "Many studies have shown that TNFAIP3 is a protein related to intestinal diseases and can promote the function of intestinal barrier." (PMID 35565618, 2022). "Although TNFAIP3 is expressed in human IEC and has been identified as a protein of interest in intestinal disease, it is not known whether TNFAIP3 plays a role in barrier function, or the regulation of tight junctions by TNF." (PMID 22031828, 2011).
infectious disease (2 papers, 2015 to 2019). A disorder directly resulting from the presence and activity of a microbial, viral, or parasitic agent in humans. "Additionally, some of these target genes, including SOD2, TNFAIP3, ARG1, SERPINB2, VLDLR, HSPA5, and LCN2, are associated with infectious diseases, suggesting that lncRNAs respond to PCV2 infection by regulating these genes." (PMID 30863688, 2019). "In addition, we analyzed the predicted target genes of differentially expressed lncRNAs, including SOD2, TNFAIP3, and ARG1, all of which are involved in infectious diseases." (PMID 30863688, 2019).
psychiatric disorder (2 papers, 2021 to 2025). A disorder characterized by behavioral and/or psychological abnormalities, often accompanied by physical symptoms. "This further supports the potential regulatory role of TNFAIP3 in psychiatric disorders, suggesting that Berbamine may improve psychological symptoms associated with COPD by influencing TNFAIP3." (PMID 41155519, 2025). "There had also been reports of abnormalities of TNFAIP3 in other psychiatric disorders." (PMID 34393859, 2021).